RYR3 (ryanodine receptor 3)
Description:
Cytosolic calcium-activated calcium channel that mediates the release of Ca(2+) from the sarcoplasmic reticulum into the cytoplasm in muscle and thereby plays a role in triggering muscle contraction. May regulate Ca(2+) release by other calcium channels. Calcium channel that mediates Ca(2+)-induced Ca(2+) release from the endoplasmic reticulum in non-muscle cells. Contributes to cellular calcium ion homeostasis (By similarity). Plays a role in cellular calcium signaling.
Synonyms: RYR-3; CMYO20; CMYP20
Tractability: Small molecule: an approved drug acts on it; a structure with a bound ligand is known; it belongs to a druggable protein family. Antibody: UniProt predicts a signal peptide or a membrane-spanning region; its Gene Ontology location is reachable by antibodies, with medium confidence. PROTAC: ubiquitination databases record sites on it.
Target class: Ligand-gated ion channel; Ion channel; Ryanodine receptor
Gene: Protein-coding gene on chromosome 15 (33,310,962 to 33,866,121, forward strand). Ensembl gene ENSG00000198838.
Subcellular location: Sarcoplasmic reticulum membrane
Subcellular location (Human Protein Atlas): Vesicles
Pathways (Reactome):
Muscle contraction: Ion homeostasis
Transport of small molecules: Stimuli-sensing channels
Gene Ontology:
Molecular function: intracellularly gated calcium channel activity; calcium-induced calcium release activity; ryanodine-sensitive calcium-release channel activity; calcium channel activity; calcium ion binding; monoatomic ion channel activity
Biological process: calcium ion transport; calcium ion transmembrane transport; cellular response to ATP; cellular response to caffeine; cellular response to calcium ion; cellular response to magnesium ion; protein homotetramerization; release of sequestered calcium ion into cytosol; release of sequestered calcium ion into cytosol by sarcoplasmic reticulum; striated muscle contraction; calcium-mediated signaling; intracellular calcium ion homeostasis; monoatomic ion transport; transmembrane transport
Cellular component: calcium channel complex; membrane; sarcolemma; sarcoplasmic reticulum membrane; smooth endoplasmic reticulum; Z disc; junctional membrane complex
Genetic constraint (gnomAD): Loss-of-function variants: 169 observed, 446.6 expected, observed/expected ratio (o/e) 0.38, 90% interval 0.33 to 0.43. The upper end of that interval is the gene's LOEUF score, 0.43, which puts it in group 1 of 6, group 1 being the genes least tolerant of losing a copy. Missense variants: 4,861 observed, 5,412.8 expected, observed/expected ratio (o/e) 0.9, 90% interval 0.88 to 0.92. Synonymous variants: 2,134 observed, 2,023.2 expected, observed/expected ratio (o/e) 1.05, 90% interval 1.02 to 1.09.
Gene-disease validity (ClinGen):
ClinGen rates the evidence that RYR3 causes each of these diseases.
genetic developmental and epileptic encephalopathy (autosomal dominant): Limited. A complex neurodevelopmental disorder characterized by a range of developmental delays and epileptic encephalopathy phenotypes.
congenital myopathy (autosomal recessive): Disputed.
Homologues: Orthologues: chimpanzee RYR3 (99% identical), macaque RYR3 (99% identical), rabbit RYR3 (97% identical), pig RYR3 (97% identical), rat Ryr3 (96% identical), mouse Ryr3 (96% identical), guinea pig RYR3 (95% identical), dog RYR3 (91% identical), tropical clawed frog RYR3 (84% identical), zebrafish ryr3 (77% identical), Drosophila melanogaster RyR (47% identical), Caenorhabditis elegans unc-68 (43% identical). Paralogues in human: RYR2 (69% identical), RYR1 (67% identical), ITPR2 (14% identical), ITPR1 (14% identical), ITPR3 (13% identical).
Diseases named in the same sentence as RYR3 in open-access papers:
RYR3 is named in the same sentence as 65 diseases in open-access papers, as found by Europe PMC text mining. Sharing a sentence is not in itself a finding about the gene and the disease. The quoted sentences say what the papers report.
Alzheimer disease (5 papers, 2020 to 2023). A progressive, neurodegenerative disease characterized by loss of function and death of nerve cells in several areas of the brain leading to loss of cognitive function such as memory and language. "In addition, studies on different Han Chinese populations showed that three SNPs, rs2033610, rs2596164 and rs2278317, in RYR3 were associated with the incidence of hypertension, diabetes and Alzheimer’s disease." (PMID 37391705, 2023). "RyR3 has recently been linked to Alzheimer’s disease in a mouse model and family-based association tests have shown that some RyR3 variants can be linked to hypertension, diabetes and Alzheimer’s disease in humans, but the details of these processes have not yet been explored." (PMID 32899693, 2020). "These modifications affecting the transcriptional activity of Ryr3 are relevant not only in the context of learning and memory, as dysregulation of Ryr3 has been observed in aging, obsessive-compulsive disorder, and Alzheimer's disease." (PMID 34434232, 2021). "Similarly, SNPs rs16972837 and rs659517, both from gene RYR3, and SNP rs607483, are involved in the same pathways 4371-Apelin Signaling Pathway, 4713-Circadian Entrainment and 5010-Alzheimer’s Disease." (PMID 35033007, 2022). "Interestingly, a biphasic effect for Ryr3 during the early and late stages of Alzheimer's disease is proposed, calling attention to gain a more in-depth insight into the transcriptional regulation of the Ryr3 gene in this context." (PMID 34434232, 2021).
epilepsy (5 papers, 2021 to 2025). A brain disorder characterized by episodes of abnormally increased neuronal discharge resulting in transient episodes of sensory or motor neurological dysfunction, or psychic dysfunction. "A search of PubMed and Google Scholar databases yielded two relevant articles reporting three cases of epilepsy/DEE attributed to RYR3 variants." (PMID 39220738, 2024). "The present case of DEE caused by a RYR3 heterozygous variant is consistent with previous rare cases of epilepsy caused by RYR3 gene variants in terms of pathogenesis and clinical features, but significantly different from congenital myopathy type 20." (PMID 39220738, 2024). "Identifying specific pathogenic variants in genes such as SCN1A, SCN9A, and QARS1 and the recurrent combination of RANBP2 and RYR3 variants underscores the necessity for ongoing research to elucidate their roles in epilepsy development." (PMID 39509559, 2024). "We also reviewed and summarized the literature on epilepsy cases caused by RYR3 gene variants." (PMID 39220738, 2024). "Additional WGS testing ruled out other variants that could be responsible for the patient’s disease, and sporadic reports suggest that RYR3 variants, particularly heterozygous missense variants, can cause epilepsy and DEE." (PMID 39220738, 2024). "Identification of potentially pathogenic variants and frequent genetic combinations, such as RANBP2&RYR3, could aid in understanding the genetic basis of epilepsy and identifying potential hotspots." (PMID 39509559, 2024). "Interestingly, the RANBP2 variants, when present as VUS, consistently co‐occurred with a variant of RYR3, suggesting a potential pathogenic role for this combination in contributing to the manifestation of epilepsy." (PMID 39509559, 2024). "The molecular genetics and clinical features of this case were consistent with three previously reported cases of RYR3-related epilepsy/DEE." (PMID 39220738, 2024). "Following analyzing the detected variants from unaffected biological parents' tests, it was observed that one RYR3 & Ranbp2 combination was inherited, with each variant originating from a different parent, suggesting that the combination of genes may be the cause of the child's epilepsy." (PMID 39509559, 2024). "Other genes with CNV losses that have an indirect relation to epilepsy are RYR3, CDH13, PCDH9, and LRRC55." (PMID 33557955, 2021). "Identifying potentially pathogenic variants like those found in SCN9A and QARS1, as well as frequently co‐occurring combinations like RYR3 and RANBP2, offers valuable insights into the genetic foundations of epilepsy." (PMID 39509559, 2024). "Furthermore, haploinsuficiency of RYR3 might cooperate in an indirect way with several membrane proteins coded by genes implicated in sodium or calcium voltage channels, including SCN1A that is also implicated in epilepsy." (PMID 33557955, 2021). "However, the widespread expression of RYR3 in the human body cannot explain how its variants lead to DEE or myopathy, two completely different clinical phenotypes, and there have been no reports of individuals having both epilepsy and myopathy." (PMID 39220738, 2024).
Hypertension (5 papers, 2020 to 2024). The presence of chronic increased pressure in the systemic arterial system. "The functions of the gene RYR3 (coding for the ryanodine receptor 3) are less straightforward since it has been linked to a variety of conditions, ranging from hypertension to diabetes." (PMID 38632466, 2024). "Common diseases may share the same risk genetic variants, for example, by applying family-based association tests, one study found that rs2033610, rs2596164, and rs2278317 variants of the Ryanodine receptor 3 (RYR3) gene were associated with risk of hypertension, T2D, and AD." (PMID 33352859, 2020).
cognitive deficits (4 papers, 2020 to 2023). "Our findings revealed a novel mechanism via which miR-124 deficiency depresses RyR3 expression to induce cognitive deficits in aged brain." (PMID 36186122, 2022). "The SNPs in ESR1 and RYR3 are of specific interest as they have been extensively studied and found to be involved with immunologic processes and brain functions, which are previously reported to be associated with cognitive impairment and decline." (PMID 33154391, 2020). "Mechanistically, miR-124 deficiency in the brain led to upregulation of the Ryanodine receptor 3 (RyR3, an intracellular calcium-release channel) and the cognitive deficits in miR-124-3 knockout mice were ameliorated by knocking down RyR3 expression using RNAi." (PMID 36186122, 2022).
atherosclerosis (3 papers, 2014 to 2017). A disease characterized by the build-up of fatty material and calcium deposition in the arterial wall resulting in partial or complete occlusion of the arterial lumen. "Nonetheless, RYR3 appears to play a role in HIV-related atherosclerosis risk based on some of the possible gene (or protein) interactions found significant in this study." (PMID 29206233, 2017). "RYR3 gene rs877087 and rs2229116 polymorphisms are associated with atherosclerosis in elderly Japanese." (PMID 24423397, 2014). "rs877087 and rs2229116 of RYR3 gene are associated with atherosclerosis severity in Japanese." (PMID 24423397, 2014). "Thus, it is conceivable that RYR3 is a good candidate for atherosclerosis susceptible gene." (PMID 24423397, 2014). "RYR3 have a major role in calcium signaling in the vasculation and thus is a good candidate gene in atherosclerosis pathogenesis." (PMID 24423397, 2014). "These lines of evidence suggest that, intracellular calcium mobilization mediated by RYR3 may be involved in atherosclerosis process through its common participants, such as arterial smooth muscle cells, endothelial cells and T lymphocytes." (PMID 24423397, 2014). "Thus, the RGS18 effect on platelets is mediated through calcium homeostasis and therefore genetic interactions between RGS18 and RYR3 gene are possible, and may play a substantial role in atherosclerosis as platelets are involved in its inflammatory response." (PMID 29206233, 2017).
breast carcinoma (3 papers, 2021 to 2023). "Previous studie has reported that the inactivation of RYR3 results in constrained growth of breast cancer cells." (PMID 38086955, 2023).
heart failure (3 papers, 2018 to 2024). Inability of the heart to pump blood at an adequate rate to meet tissue metabolic requirements. "RyR3 also occurs in cardiac muscle; single nucleotide polymorphisms in this have pharmacogenetic associations with cardiac failure." (PMID 30400228, 2018). "However, effect sizes were modest; for example, the Hazard Ratio for heart failure in RYR3 rs877087 T-allele carriers was 1.13 (95% CI 1.02–1.25) versus participants with no T alleles." (PMID 38632276, 2024). "Among these variants, rs57938337, rs6683225 and rs6692782 in RYR2 and rs12439006 and rs16958069 in RYR3 are associated with RI in Han Chinese patients with heart failure, suggesting that these variants may be used to identify patients susceptible to CRS in the future." (PMID 37391705, 2023). "We previously reported that variants in RYR3 and NUMA1 increased risks for heart failure (HF) and treatment discontinuation respectively in the same patient sample, although effect sizes were modest." (PMID 38632276, 2024). "We previously showed that alleles in genes NUMA1, RYR3, CYP3A5, ADRA1A and APCDD1 increased risks for adverse outcomes such as heart failure, coronary heart disease, and dCCB discontinuation, in 32,000 patients in UK Biobank receiving dCCB prescriptions in the primary care setting." (PMID 38632276, 2024). "The RYR3 variant rs877087 T-allele alone modestly increased heart failure risks versus non-carriers (HR:1.13, p = 0.02); in patients with high polygenic scores for fat mass, lean mass, and lipoprotein A, risks were substantially elevated (HR:1.55, p = 4 × 10−5)." (PMID 38632276, 2024).
thymoma (3 papers, 2020 to 2023). A neoplasm arising from the epithelial cells of the thymus. "Interestingly, a significant RYR3 overexpression was observed in MG thymomas, from both corticosteroid-naïve and -treated patients, compared to the non-MG thymomas, control thymuses, and hyperplastic MG thymuses." (PMID 36979710, 2023). "Accordingly, we found a significant RYR3 overexpression in MG, particularly of type B3/B3 mixed, along with A/AB, compared to non-MG thymomas, hyperplastic MG, and control thymuses, thus suggesting an association between RYR3 overexpression and autoreactivity to RYR1 developing inside the thymoma." (PMID 36979710, 2023). "Furthermore, expression of the brain-type ryanodine receptor, RYR3, in thymomas has been shown to be associated with TAMG, but in this case we now find that the association is strongest in type B2 thymomas." (PMID 32373124, 2020). "Among the genes encoding muscle-like autoantigens, NEFM and RYR3 had a more similar gene expression pattern and were clustered together in one group; they were both particularly overexpressed in type A/AB MG thymomas compared to the same tumor type in the non-MG thymoma group." (PMID 36979710, 2023). "RYR1 was also down-regulated in thymomas from anti-RYR1 antibody-positive MG patients with B3/B3 mixed thymomas, who showed a down-regulation of AIRE and an up-regulation of RYR3, compared to thymomas of the same type in seronegative non-MG patients." (PMID 36979710, 2023). "We thus assessed the NEFM, RYR3, and HSP60 expression in hyperplastic and thymoma MG thymuses, non-MG thymomas, and normal thymuses, using real-time PCR." (PMID 36979710, 2023). "The neuronal ryanodine receptor, RYR3, sharing homology with muscular RYR1, was found to be up-regulated in MG compared to non-MG thymomas by Radovich and colleagues, with the highest up-regulation being observed in the B1/B2/B3 subset." (PMID 36979710, 2023).
congenital myopathies (2 papers, 2014 to 2024). "In summary, based on the findings of this case and previous case reports, we propose that RYR3 gene variants can lead to DEE, and the RYR3 site of this type of variant has functional differences from the site of variants causing congenital myopathy." (PMID 39220738, 2024).
Epileptic encephalopathy (2 papers, 2024 to 2025). A condition in which epileptiform abnormalities are believed to contribute to the progressive disturbance in cerebral function. "Variants in the RYR3 gene (NM_001036) associated with epileptic encephalopathies in the previously reported cases and this report." (PMID 39220738, 2024). "Clinical characteristics of individuals with RYR3 variants associated with epileptic encephalopathies in the previous literature and present report." (PMID 39220738, 2024). "RYR3 was affected in another patient, EPBL-0052, a female from a consanguineous family who presented with infantile spasms and epileptic encephalopathy." (PMID 40565278, 2025).
infantile spasms (2 papers, 2024 to 2025). A rare epilepsy syndrome characterized by onset of epileptic spasms in infants between 2 and 12 months of age, and rarely up to 24 months. "The RYR3 variant in this study led to infantile spasms in the patient and subsequent significant developmental delay, even regression." (PMID 39220738, 2024). "However, based on the literature review, assuming that RYR3 variants cause infantile spasm syndrome and/or DEE, this variant is classified as pathogenic according to ACMG criteria (PS2 + PM1 + PM2 + PP3 + PP4)." (PMID 39220738, 2024). "We retrospectively analyzed the clinical characteristics and prognosis of a case of West syndrome, developmental and epileptic encephalopathy (DEE) caused by a missense variant in the RYR3 gene." (PMID 39220738, 2024). "In this study, we report a case of infantile spasm syndrome and developmental and epileptic encephalopathy (DEE) caused by a heterozygous missense variant in the RYR3 gene." (PMID 39220738, 2024). "A study found that a West syndrome patient with an RYR3 gene variant had no seizures after taking calcium antagonists such as sodium valproate, topiramate, and lamotrigine, suggesting that the patient’s seizures may be related to calcium channel defects." (PMID 39220738, 2024).
lung adenocarcinoma (2 papers, 2021). A carcinoma that arises from the lung and is characterized by the presence of malignant glandular epithelial cells. "We found that the mutation rates of TTN, PCLO, RYR3, and LRP2 in human lung adenocarcinoma were 41%, 16%, 14% and 11%, respectively, but the mutation rates of other mutant genes were <10%." (PMID 34858801, 2021).
Obesity (2 papers, 2022 to 2023). Accumulation of substantial excess body fat. "We have demonstrated that deletions in or near the SLC12A6 (Solute Carrier Family 12 Member 6) and RYR3 (Ryanodine Receptor 3) genes are statistically associated with decreased body weight and a lower risk of obesity." (PMID 37799139, 2023). "This suggests that dogs carrying a deletion at the RYR3 gene are more predisposed to excessive fat accumulation, while the risk of obesity decreases with each copy of the reference variant." (PMID 37799139, 2023). "In addition to calprotectin, we also report a downregulation of endoplasmic reticulum calcium transporter Ryr3 in the obese endometrial epithelia, suggesting that obesity-induced disruption of calcium signaling may impact innate immune processes in this cell type." (PMID 36424602, 2022).
Stroke (2 papers, 2014 to 2023). Sudden impairment of blood flow to a part of the brain due to occlusion or rupture of an artery to the brain. "Two single-nucleotide polymorphisms (SNPs) in the RYR3 gene have been shown to associate with stroke (rs877087) and carotid intima-media thickness (rs2229116) in two independent genome-wide association studies (GWAS) in Caucasian." (PMID 24423397, 2014). "The previous GWAS showed that the RYR3 gene polymorphisms rs877087 and rs2229116 was associated with stroke and cIMT, respectively." (PMID 24423397, 2014). "In particular, RYR3 (in intracellular calcium channels) was found to be associated with heart failure (HF) and there is a need to examine its effect on stroke, and effects on heart disease in risky groups as it is unknown." (PMID 36134646, 2023).